PGR (progesterone receptor)
Diseases named in the same sentence as PGR in open-access papers (continued):
Sharing a sentence is not in itself a finding about the gene and the disease.
tumor (continued). "We evaluated the associations of PSCA SNPs with various clinicopathological features including: tumor size, lymph node metastasis, and the expressions of estrogen receptor (ER), progesterone receptor (PR), and human epidermal growth factor receptor 2 (HER-2)." (PMID 27050280, 2016). "We selected significant parameters (p < 0.20) from among various conventional confounding factors and performed a multivariate analysis in which nodal metastasis, PgR, tumor grade, and Ki-67 expression served as categorical variables." (PMID 27368476, 2016). "Inhibition of miR-141 increases both CD44+ and CK5+ cells by targeting Stat5a and progesterone receptor (PR), and enhances the abilities of mammosphere formation and tumor initiation." (PMID 26349457, 2016). "The great majority of these neoplasms show estrogen and progesterone receptor positivity suggesting that AA is a hormone dependent tumor as rapid growth and recurrence have been observed during pregnancy." (PMID 27274877, 2016). "To study the effect of different cutoffs of HRs expression in TP tumors we defined a TP30 (both ER and PgR expressed in >30% of tumor cells) and a TP50 (both ER and PgR expressed in >50% of tumor cells) populations." (PMID 26910921, 2016). "Before approximately 1995, cytosol ER and PgR were measured by ligand binding or immunochemical methods measuring receptor content in tumor tissue consisting of both cancer cells and stromal cells." (PMID 27722840, 2016). "Markers for cell proliferation (Ki67), and molecular features (estrogen and progesterone receptor) were combined with optical measurements such as [HbO2], [Hb], or the tumor oxygen saturation (StO2)." (PMID 26942698, 2016). "A smaller numerical increase was seen in patients with PgR+ (38.5%) compared with PgR− (33.3%) tumours." (PMID 27174596, 2016). "Luminal tumours, as defined by oestrogen receptor (ER) and/or progesterone receptor (PgR) expression by immunohistochemistry (IHC), account for 75% of all BC, summing up to 85% in women over 70 years old." (PMID 26823678, 2016). "PgR has instead been found most frequently in normal cells than in tumor cells and has been identified as a positive prognostic factor as in our job." (PMID 27690341, 2016). "The continuous percentage PgR expression was inversely correlated with tumor grade and Ki67 hotspot index (Grade: correlation coefficient − 0.508, p < 0.001." (PMID 26970778, 2016). "It is currently standard practice to determine the pathological grade and stage of the primary tumour and to examine HRs including ER alpha (ERα) and PgR using IHC." (PMID 27189371, 2016). "MBC is a hormone-driven tumor and steroid receptors, namely the estrogen receptor (ER), progesterone receptor (PgR) and androgen receptor (AR) are often expressed." (PMID 27248471, 2016). "They found that 45 % of patients with ERα+ primary tumours had ERα− CTCs, whilst 78 % of patients with PgR+ primary tumours had PgR− CTCs." (PMID 27189371, 2016). "In our patient cohort, we analyzed tumor mtDNA content in relation to patient age at diagnosis, menopausal status, tumor size, histological grade, estrogen receptor status, progesterone receptor status and ERBB2 amplification." (PMID 27081694, 2016). "For patients with 1–9 % PgR-positive tumor cells, we observed a similar recurrence rate in both treatment arms." (PMID 27722840, 2016). "In breast cancer, the tumor-metastasis discrepancy rates are 9–18% for estrogen receptor (ER), 24–31% for progesterone receptor (PR), and ~10% for ERBB2." (PMID 27028851, 2016). "With respect to tumor biology, there was a small but significant difference between the proportions of early- and late-stage disease in the patients who had PgR-positive tumors (59.7% and 52.2%, respectively; P = 0.01)." (PMID 27336872, 2016). "Immunohistochemistry for progesterone receptor, which is strongly expressed in meningothelial cells, was used to identify interfaces of tumor and meninges unambiguously." (PMID 27255663, 2016).
tumor (continued). "The final diagnosis was pT1cN0M0, stage I. Because of the ER and PgR positivity of the tumor, the patient was treated with tamoxifen (20 mg) for 5 years." (PMID 26943416, 2015). "Of the clinicopathological characteristics of tumor grade, age, menopause status, estrogen receptor, progesterone receptor, and human epidermal growth factor receptor 2 (HER2), only absence of HER2 expression correlated with CLN3 overexpression." (PMID 26528430, 2015). "These include disease stage, age and menopausal status, the oestrogen receptor (ER) and progesterone receptor (PgR) status of the tumour, its proliferative capacity and the human epidermal growth factor receptor 2 (HER2) expression status." (PMID 26318869, 2015). "TNBC are aggressive and highly invasive, and these tumours lack estrogen receptor (ER), progesterone receptor (PR) and human epidermal growth factor 2 (HER2) expression." (PMID 26070602, 2015). "This allowed a broad separation of tumours into two prognostic groups, where univariate analysis suggested that ERα and PGR, together with other NRs acted to affect survival differences." (PMID 26280373, 2015). "A recent study showed that the distant disease-free survival (DDFS) of patients with Ki-67 <14% and PgR <20% were similar to those of patients with Ki-67 <14% and PgR ≥20% in ER+/HER2- tumours, which supports our assumption." (PMID 25938238, 2015). "On immunohistochemical staining, the nuclei of smooth muscle cells in the tumor were positive for estrogen receptor (ER) and progesterone receptor (PR)." (PMID 26236515, 2015). "A number of prognostic and treatment predictive factors have been identified such as tumour size, oestrogen (ER) and progesterone (PgR) receptor status, human epidermal growth factor receptor type 2 (HER2) status, histological grade, Ki67 and age." (PMID 25991917, 2015). "Thirdly, there is limit prognostic information stratified by tumor stage, progesterone receptor status and treatment modality." (PMID 26305693, 2015). "ER+/PgR-/HER2- tumours showed poorer clinicopathologic characteristics relative to ER+/PgR+/HER2- tumours using a PgR threshold of 20% instead of 1%." (PMID 25938238, 2015). "ER+/PgR-/HER2- tumours were observed in older patients at diagnosis, and these tumours were larger, generated more metastatic lymph nodes, a lower level of ER expression and a higher proliferation rate." (PMID 25938238, 2015). "The differences between luminal A and luminal B tumours depend on the choice of the threshold value for Ki-67 and the requirement for PgR positivity." (PMID 25938238, 2015). "In summary, our study found that ER+/PgR-/HER2- tumours present more unfavourable clinicopathologic characteristics than ER+/PgR+/HER2- tumours." (PMID 25938238, 2015). "Our results primarily confirm that patients with ER+/PgR-/HER2- tumours display more unfavourable clinicopathologic characteristics compared with patients with ER+/PgR+/HER2- tumours, which affirms the prognostic importance of PgR expression." (PMID 25938238, 2015). "Tumor biomarkers including estrogen receptor (ER), progesterone receptor (PR), human epidermal growth factor receptor 2 (HER2) and Ki-67 are routinely tested in breast cancer patients and their status guides clinical management and predicts prognosis." (PMID 26384297, 2015). "In this study, we aimed to assess the clinicopathologic characteristics of ER+/PgR-/HER2- tumours by comparing them with ER+/PgR+/HER2- tumours using a PgR cut-off point of 20% as a divisive criterion." (PMID 25938238, 2015). "After chemotherapy, he was treated with tamoxifen (20 mg) due to the ER and PgR positivity of the tumor." (PMID 26943416, 2015). "The expression levels of ER and PR were directly correlated with the favourability of the clinicopathologic characteristics in ER+/PgR+/HER2- tumours." (PMID 25938238, 2015).
tumor (continued). "PN serum levels were not correlated with the clinical pathological parameters selected for the present analysis, except for tumor PgR status (p = 0.02), patient age at surgery (p = 0.005), and adjuvant systemic therapy (p = 0.04)." (PMID 26225965, 2015). "Increasing tumor size has been reported to be associated with increased breast cancer-specific mortality (BCSM) within each joint estrogen receptor (ER) and progesterone receptor (PR) status category." (PMID 26036636, 2015). "Tumor size, lymph node status, histological grade, ER, PgR and HER-2 status, Ki67-index, neoadjuvant treatment, CAIX expression and lesional TVP/area were not significantly different between IBCs in the two PAM image groups." (PMID 26506106, 2015). "The most important clinical classification of this tumor is based on the determination of ER (estrogen receptor), PR (progesterone receptor) and HER2 (human epidermal growth factor receptor-2) receptors." (PMID 26313912, 2015). "The synthetic anti-progestin RU-486, which acts by blocking the progesterone receptor (PR), inhibits progestin-dependent tumor growth, indicating that the process is dependent on PR." (PMID 26312209, 2015). "The tumor suppressor p27 is frequently deregulated in breast cancer, and reduced p27 expression has been associated with increased proliferation, high tumor grade, HER2 amplification as well as estrogen receptor (ER) and progesterone receptor (PR) negativity." (PMID 25925673, 2015). "We also validated the accuracy of this classification and aimed to further elucidate the clinicopathologic features of ER+/PgR-/HER2- tumours by comparing them with ER+/PgR+/HER2- tumours." (PMID 25938238, 2015). "Regarding tumor biology, 64.5 % (49 out of 76) and 53.2 % (42 out of 77) were positive for estrogen- and progesterone receptor respectively." (PMID 26169261, 2015). "The final diagnosis was pT1bN0M0, stage I. Because of the ER and PgR positivity of the tumor, the patient was treated with tamoxifen (20 mg) for 5 years." (PMID 26943416, 2015). "These factors include patient age, histological type and grade, tumor size, lymph node status, estrogen receptor (ER) and progesterone receptor (PR) status, and human epidermal growth factor receptor 2 (HER-2) status." (PMID 26405632, 2015). "For the Breast1 cohort, we included factors such as age, lymph node status, histological grade, tumor size, estrogen receptor (ER) status, and progesterone receptor (PR) status." (PMID 25146220, 2014). "In our population 79% of patients (n = 563) had a tumor that was estrogen- and/or progesterone-receptor positive." (PMID 25279326, 2014). "• The subgroup of 301 patients with the ER+PgR+ phenotype of Luminal B1 tumors showed even a higher rate of tumor invasion." (PMID 24917206, 2014). "The results showed 632 patients fulfilled the inclusion criteria, with the median age being 55 years (range: 28–95), and 559 (88.4%) patients presented with estrogen receptor and/or progesterone receptor positive tumours." (PMID 25114720, 2014). "No statistical difference was found between the diversin overexpression and age (p = 0.9263), tumor size (p = 0.2371), ErbB2 status (p = 0.4613) and progesterone receptor status (p = 0.1054)." (PMID 24858714, 2014). "There was a significant decrease in the expression of estrogen receptor (ER) and progesterone receptor (PR) both in tumor tissue and cells after treatment with taspine." (PMID 24876877, 2014). "cT (tumor size), cN (lymph node), PR (progesterone receptor), and HER2 status predicted bone metastasis (P < 0.05)." (PMID 24628817, 2014). "Immunohistochemistry (IHC) revealed that the tumor cells were positive for desmin, estrogen receptor, progesterone receptor and vimentin; the Ki-67 proliferation index was less than 5%." (PMID 24894537, 2014). "Beside that in all three tumor types with positive steroid receptors (Luminal A, B1 and B2), the dysfunctional ERs in the ER+PgR− phenotype showed slower rates of tissue invasion." (PMID 24917206, 2014).
tumor (continued). "We showed that levels of expression of NAT1 were positively correlated with ERα and PgR, but negatively correlated with tumor grade and size." (PMID 25528056, 2014). "Luminal breast cancer, a molecular tumour classification subtype, is characterised by being estrogen receptor (ER) and/or progesterone receptor (PR) positive and responding well to endocrine therapy." (PMID 25073969, 2014). "We subsequently analyzed the relationship of JMJD2A expression with tumor regulators including estrogen receptor (ER)α, progesterone receptor (PR), HER2 and ARHI." (PMID 24886710, 2014). "CD 99 and the progesterone receptor were positive in both tumor components, inhibin and calretinin only in the granulosa cells, and pancytokeratin only in the sarcomatouse one." (PMID 24894598, 2014). "One hundred and seventy-six (56%) of patients had estrogen receptor (ER) and 130 (42%) of patients had progesterone receptor (PR) positive tumours." (PMID 25435855, 2014). "Univariate analysis indicated significant associations between levels of ERα (P = 0.0034), PgR (P = 0.0221), NAT1 (P = 0.0054), tumor size (P = 0.0188), number of positive lymph nodes (P = 0.0048) and OS." (PMID 25528056, 2014). "A significant positive correlation (r = 0.26) was seen between Ki67 and histological grade (p < 0.001), but not between Ki67 and other prognostic factors (nodal status, ER, PgR, age and tumour size)." (PMID 24567879, 2014). "Levels of NAT1 were positively correlated with ERα (P < 0.0001) and PgR (P < 0.0001), but negatively correlated with tumor grade and size (P < 0.0001)." (PMID 25528056, 2014). "Nuclear DACH1 expression was strongly increased in patients with ER-alpha positive tumours co-expressing PgR, and epithelial CK18/19 cytokeratins." (PMID 24392136, 2014). "We found significant differences in the stage, tumor size, the number of positive nodes, histological grade and the progesterone receptor." (PMID 25085350, 2014). "In a multivariable model, including adjuvant treatment, age, tumour size, nodal status, histological grade, ER, PgR and Ki67, the only significant prognostic factor for BCM was nodal status (p < 0.001)." (PMID 24567879, 2014). "Estimated by Freedmans%, diagnostic age, tumour size, ALNI, grade, ER and PgR explained 55.6% of the observed differences in mortality between non-symptomatic and symptomatic cases." (PMID 24678853, 2014). "Progesterone receptor was positive in 72% (162/224) of ER-positive tumours and 12% (14/120) of ER-negative tumours." (PMID 25433805, 2014). "Levels of expression of NAT1 were positively correlated with those of ERα (P < 0.0001) and PgR (P < 0.0001), but negatively correlated with both tumor grade and size (P < 0.0001)." (PMID 25528056, 2014). "Chi-square analyses showed that there were significant differences between the four patient groups in ER (p = 0.019), PgR (p = 0.007), tumor grade (p < 0.001) and systemic therapy (p = 0.010), for which we corrected in the multivariate analyses." (PMID 25139823, 2014). "In a subgroup analysis of ERα-positive and PgR-positive patients, Bostner and colleagues recently observed a reduced benefit from tamoxifen in those patients whose tumor expressed high p-mTOR." (PMID 24447434, 2014). "We had information on immunohistochemical status on matched primary tumours and BM in 14 pts for ER and PgR, and in 16 pts for HER-2." (PMID 23634179, 2013). "In the Stockholm 3 cohort, the outcome among patients with ER-positive/PgR-positive tumours treated with tamoxifen was evaluated in relation to 4EBP1 protein expression in different compartments." (PMID 24131622, 2013). "The following covariates were registered at primary diagnosis: patient’s age, menopausal status, number of positive axillary lymph nodes, tumour location, tumour size, histologic tumour grade, oestrogen, and progesterone receptor status." (PMID 23786493, 2013). "Tumor ER and/or PgR positivity is a prerequisite for responsiveness to targeted therapy with an endocrine agent." (PMID 23972025, 2013).
tumor (continued). "A significantly higher proportion of cases expressed PgR and showed a Ki-67 ≤20% among screen detected cancers compared with symptomatic tumours (78.1% vs. 68%, p=0.04 and 57.1% vs. 44.1%, p=0.02, respectively)." (PMID 23305429, 2013). "WT1 was associated with tumor grade (P = 0.025) and RSPO1 was associated with progesterone receptor expression (P = 0.019)." (PMID 24373193, 2013). "The 7 clinical annotations for each tumour/patient were: lymph node (LN) status; hormone receptor status (estrogen receptor (ER) status and progesterone receptor (PgR) status); tumour grade; tumour subtype; tumour size; patient age." (PMID 23405961, 2013). "In a subsequent analysis, the benefit from tamoxifen was compared between patients with ER-positive/PgR-positive tumours expressing low or high cytoplasmic levels of p4EBP1 or 4EBP1." (PMID 24131622, 2013). "ER, progesterone-receptor (PgR) and Ki67 expression were determined from tumor biopsies before treatment and at surgery." (PMID 23497452, 2013). "Only patient’s age, number of positive lymph nodes, tumour size, tumour grade and progesterone receptor status were considered." (PMID 23786493, 2013). "Immunohistochemical staining was positive for synaptophysin, NSE, CK7, and ER in almost all the tumor cells; however, PgR was positive only focally." (PMID 23738176, 2013). "Among protein markers, only tumor PgR positivity correlated significantly with longer survival (p = 0.022)." (PMID 23935969, 2013). "The exclusive occurrence of these tumors in young females, along with the positive presence of progesterone receptor markers, supports the theory that hormones have affects on the tumor development." (PMID 23760027, 2013). "We stratified by study region, tumor grade, and estrogen/progesterone receptor status, and adjusted for age, tumor size, nodal status, metastases (stage I–IV only), menopausal hormone treatment, mode of detection, radiotherapy, and smoking." (PMID 24086446, 2013). "Patient and primary tumor characteristics (estrogen receptor (ER), progesterone receptor (PR), HER2, EGFR, and Ki67) were evaluated." (PMID 24490077, 2013). "A high infiltration by FOXP3+ lymphocytes was significantly associated with tumor grade III (P<0.001), HER2 positivity (P=0.03), ER negativity (P<0.001) and a triple-negative phenotype (ER−/PgR−/HER2−) (P=0.003)." (PMID 24649219, 2013). "The Panel recommended a cut-off of a minimum of 1% of tumor cells positive for ER/PgR for a specimen to be considered positive." (PMID 23972025, 2013). "The Wilcoxon Signed Rank Test was used to evaluate differences in ER and PgR expression from the primary tumour to the metastatic tissue in the brain." (PMID 23634179, 2013). "A meta-analysis suggests that the association between BMI and BC risk is heterogeneous according to estrogen receptor (ER) and progesterone receptor (PR) status of the tumor." (PMID 23431300, 2013). "Tumor sections were stained for progesterone receptor (PGR), as PGR expression is mediated by ER signaling and its increased expression correlates with ER activation." (PMID 24176089, 2013). "Particularly, comparing the immunohistochemical data, we observed that none of the patients had a change of the HER-2 status, while three and four patients, respectively, lost the expression of ER or PgR from primary tumour to brain metastasis." (PMID 23634179, 2013). "Tumour levels of hormone receptors, ER α and PgR, and dynamic range of assessment methodology impact indications for the presence of hormone receptors." (PMID 23972025, 2013). "This particular subgroup of patients has a more favorable tumor profile in terms of ER/PgR and HER2 than the subgroup with high VEGFR1 levels." (PMID 23146280, 2012).